GDF11 (growth differentiation factor 11)
Diseases named in the same sentence as GDF11 in open-access papers (continued):
Sharing a sentence is not in itself a finding about the gene and the disease.
atherosclerosis (6 papers, 2017 to 2023). A disease characterized by the build-up of fatty material and calcium deposition in the arterial wall resulting in partial or complete occlusion of the arterial lumen. "Recombinant GDF11 gene transfer (AAV-GDF11) promoted the protection of injured endothelium, attenuated apoptosis, and reduced expression of innflammatory markers Tnf, Il1b, Mcp1, Il6 in an experimental atherosclerosis model in mice." (PMID 37138633, 2023). "On cardiovascular study, GDF11 could decrease endothelial apoptosis and inflammation against atherosclerosis in aging mice." (PMID 33597668, 2021). "By searching miRs target gene predicting database and available published reference, we found 17 potential miR-92a target genes related to vascular inflammation and atherosclerosis and only 3 with anti-atherogenic properties, which are RGS3, KLF2 and GDF11." (PMID 29777114, 2018).
heart failure (6 papers, 2018 to 2024). Inability of the heart to pump blood at an adequate rate to meet tissue metabolic requirements. "Circulating GDF11 levels represent an important negative regulator of hypertrophic and remodeling processes, which contribute to heart failure." (PMID 29783655, 2018). "Moreover, the degree of plasma GDF11 concentration increase is dependent on the severity of heart failure, suggesting that GDF11 is an adjustable mediator in cardiac remodeling." (PMID 29783655, 2018). "The known myokines related to heart failure originating from skeletal muscle are primarily decorin, irisin, myonectin, brain-derived neurotrophic factor (BDNF), growth differentiation factor-11 (GDF-11), myostatin, and osteonectin." (PMID 39203852, 2024).
Hepatic fibrosis (6 papers, 2020 to 2024). The presence of excessive fibrous connective tissue in the liver. "Similarly, while GDF11 has been implicated in exacerbating liver injury, it has also been shown to have the potential to reduce liver fibrosis." (PMID 38494851, 2024). "This process may explain the underlying mechanism through which GDF11‐induced LGR5+ cells decrease liver fibrosis." (PMID 38494851, 2024). "Growth differentiation factor 11 (GDF11) protein is one of the emerging targets with beneficial effects on reducing liver fibrosis and cirrhosis." (PMID 38494851, 2024). "A similar effect was reported for GDF11, e.g., GDF11 is upregulated in human fibrotic liver and ameliorated liver fibrosis in CCl4-treated mice by promoting LGR5 + LPC expansion." (PMID 37798809, 2023). "The aim of the present study was to specifically characterize the potential role of GDF11 in liver fibrosis, including the progression of NAFLD to NASH." (PMID 33126224, 2020). "GDF11-treated ob/ob mice displayed significantly more perivenular liver fibrosis (1.64%±48 of total imaged liver area) compared to CTL mice (0.58%±25) (p<0.001)." (PMID 33126224, 2020). "Consequently, further investigations are required to determine the exact mechanism and potential therapeutic effects of GDF11 in liver fibrosis." (PMID 38494851, 2024). "Additionally, GDF11 analogues play pivotal roles in liver‐associated diseases like NAFLD, HCC and liver fibrosis." (PMID 38494851, 2024). "In previous studies, GDF11 was shown to have controversial effects on liver fibrosis and cirrhosis." (PMID 38494851, 2024). "In patients with liver fibrosis and mouse models of experimentally induced liver fibrosis, observations regarding the upregulation of GDF11 expression imply that therapeutic application of GDF11 may resist fibrosis onset." (PMID 33886503, 2021). "Furthermore, GDF11 mRNA levels tended to correlate with progression of liver fibrosis stages (F0 to F4) in our cohort." (PMID 33126224, 2020). "However, the role of GDF11 in liver fibrosis is controversial." (PMID 38143761, 2023). "In mouse models of hepatic fibrosis, LGR5+ LPCs treated with GDF11 suppressed fibrogenesis." (PMID 38494851, 2024). "Conversely, others have reported that GDF11 impairs the development of HFD-induced NAFLD and the transition to liver fibrosis: in these studies, GDF11 was delivered by hydrodynamic injection-mediated gene transfer, or by adenoassociated virus vectors (AAV), respectively." (PMID 33126224, 2020). "Also, incubating LX2 cells with either GDF11 or TGF-β for 24 h led to significantly elevated mRNA levels of MMP2, αSMA/ACTA2, Col1A1 and Col5A1 — markers for stellate cell activation and liver fibrosis." (PMID 33126224, 2020).
pancreatic cancer (6 papers, 2020 to 2025). "The Human Protein Atlas database shows that GDF11 is implicated in colorectal, liver, breast, and pancreatic cancers." (PMID 38611614, 2024). "GDF11 was remarkably downregulated in PCa, which inhibited tumor growth by promoting apoptosis of pancreatic cancer cells." (PMID 36741321, 2023). "A study showed that GDF11 regulates the biological behaviors of pancreatic cancer cells to influence their differentiation and high expression of GDF11 is associated with favorable OS in pancreatic cancer." (PMID 33302876, 2020). "In addition, the overexpression of GDF11 was found to suppress aggressive behaviors in pancreatic cancer cells, possibly attributable to its apoptosis-promoting effect on these cells." (PMID 38611614, 2024).
Alzheimer disease (5 papers, 2020 to 2023). A progressive, neurodegenerative disease characterized by loss of function and death of nerve cells in several areas of the brain leading to loss of cognitive function such as memory and language. "Among the differentially expressed proteins, there were proteins involved either in the neurogenic process (e.g. GDF11) or in Alzheimer’s disease (e.g. LRRK2, RCAN1, NTRK2), or in both neurogenesis and Alzheimer’s disease (e.g. CREBBP, SFRP1, IL1RAP)." (PMID 36703180, 2023). "Administration of GDF11 reduced cognitive deficits and amyloid deposition in a mouse model of Alzheimer’s disease and resulted in vascular remodeling and neurogenesis in older wild-type mice." (PMID 32365331, 2020). "Moreover, in neurologic system, the neuro-inflammatory activity was significantly decreased in Alzheimer’s disease model after GDF11 treatment." (PMID 33597668, 2021). "A recent study highlighted that GDF11 treatment reduced both mRNA and protein levels of GFAP and Iba1 in a mouse model of Alzheimer’s disease, suggesting a role of GDF11 in attenuation of neuroinflammation." (PMID 32365331, 2020).
ischemic stroke (5 papers, 2020 to 2025). A stroke disorder caused by obstruction of blood flow to the brain, due to thrombotic (local blood clot formation) or embolic (due to a blood clot or other material traveling from another site) event. "CircUCK2 is also essential in ischemic stroke, and overexpression of it improved neurological deficits via the circUCK2/miR-125b-5p/Growth Differentiation Factor 11 (GDF11) axis." (PMID 35205613, 2022). "Recent studies have suggested that VNS-mediated angiogenesis after an ischemic stroke is associated with the expression of angiogenic factors, such as brain-derived neurotrophic factor (BDNF), VEGF, and growth differentiation factor-11 (GDF11)." (PMID 36389255, 2022). "Given its effectiveness on the vascular system and the ability of GDF-11 to modulate age-related neuronal dysfunction, we hypothesize that GDF-11 could be an ideal candidate as a neuroprotective agent for ischemic stroke." (PMID 33013673, 2020). "VNS-mediated angiogenesis after ischemic stroke is related to the expression of angiogenic factors such as vascular endothelial growth factor (VEGF), endothelial nitric oxide synthase (eNOS), BDNF, and growth differentiation factor 11 (GDF-11)." (PMID 39996843, 2025).
myelodysplastic syndrome (5 papers, 2016 to 2024). A clonal hematopoietic disorder characterized by dysplasia and ineffective hematopoiesis in one or more of the hematopoietic cell lines. "In myelodysplastic syndrome (MDS) patients, high GDF11 levels in high-risk MDS patients was accompanied by low RBC numbers, hemoglobin concentration and hematocrit values implying that GDF11 negatively correlated with late erythropoiesis." (PMID 29113418, 2017). "Previous studies have demonstrated that GDF11 has a critical role in normal erythropoiesis as well as the pathology of β-thalassemia, myelodysplastic syndrome (MDS), and erythropoietin-resistant anemia in hemodialysis (HD) patients." (PMID 29113418, 2017). "In myelodysplastic syndrome (MDS) patients, GDF11 serum concentration is negatively correlated with late erythropoiesis." (PMID 33669537, 2021).
breast carcinoma (4 papers, 2022 to 2025). "Further investigations are warranted to elucidate the precise mechanisms underlying GDF11 signaling in breast cancer development." (PMID 38611614, 2024). "In this study, we investigated the association between GDF11 and breast cancer, and identified three key findings regarding GDF11 expression patterns, GDF11 H-score, and correlation analysis." (PMID 38611614, 2024). "Our recent study has shown that GDF11 is a promising molecule involved in the predisposition of osteolytic bone metastasis in breast cancer." (PMID 37333824, 2023). "GDF11 was screened as the most promising gene associated with the homing, osteoclastogenesis and osteoblastogenesis in the bone metastasis of the breast cancer." (PMID 35685372, 2022). "Furthermore, our study lacks detailed information on the molecular mechanisms underlying the function of GDF11 in breast cancer pathogenesis." (PMID 38611614, 2024). "Nevertheless, the relationships between clinicopathological characteristics and GDF11 expression in patients with breast cancer have yet to be clarified." (PMID 38611614, 2024). "Protein growth differentiation factor 11 (GDF11) plays crucial roles in cellular processes, including differentiation and development; however, its clinical relevance in breast cancer patients is poorly understood." (PMID 38611614, 2024). "Further research employing diverse methodologies is warranted to fully elucidate the role of GDF11 in breast cancer." (PMID 38611614, 2024). "Overall, our findings contribute to our understanding of the complex interplay between GDF11 expression and breast cancer progression, potentially paving the way for the development of novel diagnostic, prognostic, and therapeutic approaches in breast cancer management." (PMID 38611614, 2024). "Hence, the aim of this study was to investigate the expression pattern of GDF11 in patients with breast cancer using immunohistochemistry (IHC) in tumorous, ductal carcinoma in situ (DCIS), and non-tumorous tissues." (PMID 38611614, 2024). "This suggests that GDF11 may induce alterations in erythropoiesis or changes in RBC morphology within the context of breast cancer." (PMID 38611614, 2024). "GDF11, CD151, PAFAH1B2 and YTHDF2 may play a pivotal role in the predisposition of metastasis to the bone from breast cancer, whilst DPP9, FAS, ZNF519, RPP14 and FAU may be actively involved in the adaptative colonisation of metastatic breast cancer cells in bone." (PMID 35685372, 2022). "BMP2, BMP4, GDF11 and TGFBR2 had relatively higher levels in bone metastases of breast cancer while BMP5, BMP7, BMPR2, BMPR1A and ACVR2A presented lower expression in the bone metastases, in the E-MTAB-4003 dataset." (PMID 37333824, 2023). "Second, GDF11 H-score: the lower GDF11 H-score in the patients with larger tumor sizes, advanced pathological stages, and specific molecular subtypes of breast cancer (such as luminal B HER2-negative and triple-negative subtypes) implies that GDF11 exerts a potential tumor-suppressive role." (PMID 38611614, 2024). "First, GDF11 expression patterns: the observation of higher expressions in DCIS and normal tissue specimens compared to tumorous specimens suggests that GDF11 potentially plays a role in the early stages of breast cancer development." (PMID 38611614, 2024). "In addition, the IHC analysis revealed GDF11 expression in the cytoplasm and focal membrane of all examined tissues, including breast cancer, DCIS, and non-tumor tissues." (PMID 38611614, 2024). "In the present study, despite observing negative correlations between GDF11 H-score and neutrophil count, RDW-SD, and RDW-CV in the breast cancer patients, further investigations are warranted to clarify systemic GDF11 levels in these patients, as they were not measured in this study." (PMID 38611614, 2024).
breast carcinoma (continued). "We enrolled 68 breast cancer patients who underwent surgery at our hospital and assessed the expression of GDF11 in tumorous, ductal carcinoma in situ (DCIS), and non-tumorous tissues using immunohistochemical staining, with interpretation based on histochemical scoring (H-score)." (PMID 38611614, 2024). "Hence, the higher expression of GDF11 in both DCIS and normal tissue specimens in this study may be attributed to the role of GDF11 in regulating cell growth and preventing the progression of pre-cancerous lesions in breast cancer." (PMID 38611614, 2024).
cholangiocarcinoma (4 papers, 2022 to 2025). A carcinoma that arises from the intrahepatic biliary tree (intrahepatic cholangiocarcinoma) or from the junction, or adjacent to the junction, of the right and left hepatic ducts (hilar cholangiocarcinoma). "Exosomes deliver miR-3124-5p into cholangiocarcinoma cells to suppress GDF11 expression and promote the malignant progression of cholangiocarcinoma." (PMID 39735680, 2025). "Exosomes of patients with cholangiocarcinoma exhibited elevated miR‐3124‐5p levels which contribute to cancer cell proliferation migration and angiogenesis through downregulation of GDF11 expression." (PMID 38494851, 2024). "A recent study has shown upregulation of PCSK5 and GDF11 in cholangiocarcinoma patients." (PMID 38494851, 2024). "Consequently, downregulation of GDF11 may be responsible for enhancing cholangiocarcinoma aggression." (PMID 38494851, 2024).
depression (4 papers, 2023 to 2025). "Evidence indicates that weakened GDF11 signaling increases the risk of depression by enhancing the inflammatory response and increasing astrocyte activity." (PMID 40958792, 2025). "Correlation analysis revealed that serum TGF-β1 and GDF11 were negatively associated with depression severity, while GDF15 levels showed a positive correlation." (PMID 40958792, 2025). "Regarding associations among the core biomarkers and depression severity, GDF11 was negatively correlated with GDF15 (r=-0.643, p<0.01) and HAMD-17 scores (r=-0.663, p<0.01), while showing a positive correlation with TGF-β1 (r=0.493, p<0.01)." (PMID 40958792, 2025). "This role for GDF11 sheds light on its mechanism of action in the brain and allows for future therapeutic interventions in the context of depression associated with aging." (PMID 37118117, 2023). "Serum levels of GDF11 are inversely associated with depression in patients." (PMID 37118117, 2023). "Owing to its potential to modulate neurogenesis and cognitive function, GDF11 has recently emerged as a prominent focus in depression research." (PMID 40958792, 2025). "These markers also demonstrated strong correlations with depression severity: GDF15 was positively associated, while TGF-β1 and GDF11 were negatively correlated." (PMID 40958792, 2025). "The final regression model was expressed by the equation: Depression severity = 29.260 − 1.254* TGF−β1− 0.032* GDF11 + 0.02* GDF15." (PMID 40958792, 2025). "Here, we report that systemic GDF11 treatment in aged mice was sufficient to prevent memory decline and depression-like behavior, enhance hippocampal neurogenesis and autophagy and reduce hippocampal senescence." (PMID 37118117, 2023). "Here, we demonstrate that systemic administration of growth differentiation factor 11 (GDF11) in aged mice improves memory and alleviates senescence and depression-like symptoms in a neurogenesis-independent manner." (PMID 37118117, 2023). "Using the corticosterone (CORT)-induced murine model of depression-like behavior, we demonstrated that GDF11 inhibited a depression-like phenotype in young mice." (PMID 37118117, 2023). "During the last 2 weeks of treatment, mice were subjected to behavioral tests to assess the effect of GDF11 on depression-like and anxiety-like phenotypes." (PMID 37118117, 2023). "Moigneu, Abdellaoui and colleagues show that GDF11 attenuates depression-like behavior and improves memory in aged mice through neuronal autophagy and mTOR." (PMID 37118117, 2023). "As far as we know, this is the first study to specifically focus on adolescent populations in this context.Our findings suggest that TGF-β superfamily members- particularly GDF15, TGF-β1, and GDF11-may play important roles in the pathophysiology of depression." (PMID 40958792, 2025). "Furthermore, as a modulator of functional neuronal firing, GDF11 not only promotes neurogenesis and neuronal autophagy but also alleviates depression-like behaviors." (PMID 40958792, 2025). "Notably, both TGF-β1 and GDF11 are inversely correlated with depression severity, which is consistent with previous studies, further supporting their potential role as a moderator of disease progression." (PMID 40958792, 2025). "Citalopram exposure induced changes in ANKRD37 and GDF11, important for hippocampal volume, Interestingly, in mice, infusion of GDF11 enhanced hippocampal neurogenesis and attenuated depression-like symptoms." (PMID 39055655, 2024). "Overall, the score of GDF11-treated mice suggests improved symptoms of depression-like phenotype." (PMID 37118117, 2023). "To investigate whether GDF11 could have an antidepressant effect in mice, we used a well-established preclinical model of depression-like phenotype based on chronic treatment with CORT34." (PMID 37118117, 2023). "Therefore, the vast panel of behavioral tests demonstrates that GDF11 administration specifically improves memory and depression-like phenotype." (PMID 37118117, 2023).
depression (continued). "Given the tight links among hippocampal neurogenesis, depression and memory, we examined how GDF11 could be involved." (PMID 37118117, 2023). "This study provides compelling evidence for the dysregulation of TGF-β superfamily members in depression and highlights the potential of GDF15, TGF-β1, and GDF11 as promising biomarkers for both diagnosis and severity assessment." (PMID 40958792, 2025). "Additionally, we observed markedly reduced peripheral serum levels of both TGF-β1 and GDF11 in the MDD group, aligning with findings from other studies that also reported substantial decreases in these proteins among individuals with depression." (PMID 40958792, 2025). "After controlling for age, gender and BMI, the analysis revealed that TGF-β1 and GDF11 were significant negative predictor of depression severity (both p <0.001), while GDF15 showed significant positive predictive relationship (p<0.001)." (PMID 40958792, 2025). "Finally, we revealed that GDF11 levels were decreased in young adults with MDD or presenting a current depressive episode, making it a potential biomarker of depression and a possible agent for therapeutic interventions." (PMID 37118117, 2023).
Hyperglycemia (4 papers, 2019 to 2024). An increased concentration of glucose in the blood. "Overexpression of GDF11 provided a new strategy for diabetic patients to treat heart injury induced by hyperglycemia." (PMID 34262905, 2021). "In this way, GDF11 preserves β-cells by preventing hyperglycemia-induced apoptosis, but not by inducing proliferation." (PMID 39872377, 2024).
lung carcinoma (4 papers, 2019 to 2021). "Inhibition of KDM4C with shRNAs or SD70 treatment reduced the basal expression levels of TGF-β2, BMP2 and JUND while increasing the expression level of GDF11 in lung cancer cells." (PMID 33558705, 2021).